ZBTB45P1 (zinc finger and BTB domain containing 45 pseudogene 1)
Gene: Processed pseudogene on chromosome 2 (109,986,939 to 109,988,394, reverse strand). Ensembl gene ENSG00000225108.
Diseases named in the same sentence as ZBTB45P1 in open-access papers:
ZBTB45P1 is named in the same sentence as 2 diseases in open-access papers, as found by Europe PMC text mining. Sharing a sentence is not in itself a finding about the gene and the disease. The quoted sentences say what the papers report.
head and neck squamous cell carcinoma (1 paper, 2021). A squamous cell carcinoma that arises from any of the following anatomic sites: lip and oral cavity, nasal cavity, paranasal sinuses, pharynx, larynx, and salivary glands. "Another group of five pseudogenes in head and neck squamous cell carcinoma (HNSCC), LILRP1, RP6-191P20.5, RPL29P19, TAS2R2P, and ZBTB45P1, can be used as prognostic or predictive markers." (PMID 34947885, 2021).
ZBTB45P1 also shares sentences with these, for which no sentence is quoted: tumor (1 paper).